SFRP2 (secreted frizzled related protein 2)
Diseases named in the same sentence as SFRP2 in open-access papers (continued):
Sharing a sentence is not in itself a finding about the gene and the disease.
gastric cancer (continued). "There was extensive methylation in the promoter region of the MKN28 cell lines and gastric cancer tissue with low or silenced SFRP2 expression, whereas a very few methylated CpG sites were detected in adjacent non-cancer gastric tissues." (PMID 17848950, 2007). "Forced expression of SFRP2 induced cell apoptosis, inhibited proliferation of gastric cancer cells and suppressed tumour growth in vivo." (PMID 17848950, 2007). "Forced expression of SFRP2 in gastric cancer cell line MKN45 with hypermethylated SFRP2 inhibits cell proliferation, induces cell apoptosis, and inhibits in vivo tumour growth." (PMID 17848950, 2007). "Actually, one study found that the methylation level of SFRP2 in gastric cancer is higher than that in adjacent normal tissue, whereas a recent report showed that the mRNA level of SFRP2 is among the highest in advanced stages of gastric cancer and correlated with worse survival." (PMID 35372028, 2022). "It was recently reported that levels of SFRP1 and SFRP2 transcription correlate inversely with the methylation levels in samples of gastric mucosa, with or without H. pylori infection, as well as background mucosa in gastric cancers." (PMID 32092099, 2020). "Demethylation treatment restored the expression of SFRP2 in gastric cancer cell lines." (PMID 17848950, 2007). "To test this speculation, we examined the effect of SFRP2 transfection on cell proliferation and apoptosis of gastric cancer cells." (PMID 17848950, 2007). "We further demonstrated that SFRP2 could act as a functional tumour suppressor gene in gastric cancer." (PMID 17848950, 2007). "The functional role of SFRP2 in gastric cancer cells remains unclear and was further evaluated by examining the inhibitory effect of SFRP2 expression on tumour cells." (PMID 17848950, 2007). "SFRP2 was silenced in all seven human gastric cancer cell lines." (PMID 17848950, 2007). "Taken together, these data highly suggest that SFRP2 acts as a functional tumour suppressor gene in gastric cancer and its silencing may enhance tumour growth and expansion." (PMID 17848950, 2007). "Promoter methylation of SFRP2 was specifically associated with low or absent mRNA expression in gastric cancer." (PMID 17848950, 2007). "In addition, we confirmed that the SFRP2 expression was restored after the demethylating agent, 5-aza-2′-deoxycytidine, treatment in gastric cancer cell lines." (PMID 17848950, 2007). "In conclusion, we found that SFRP2 is hypermethylated in gastric cancer." (PMID 17848950, 2007). "In light of the observed anti-proliferative and pro-apoptotic effects of SFRP2 on MKN45 in vitro, we tested whether SFRP2 would alter the growth of gastric cancer cells in vivo." (PMID 17848950, 2007). "In conclusion, epigenetic inactivation of SFRP2 is a common and early event contributing to gastric carcinogenesis and may be a potential biomarker for gastric cancer." (PMID 17848950, 2007). "We previously showed that SFRP1, SFRP2 and SFRP5 are frequently inactivated in CRC and gastric cancer (GC), and that SFRPs suppress constitutive Wnt signalling when overexpressed in CRC and GC cells." (PMID 18283316, 2008). "The SFRP2 gene has been published several times in relation to both CRC and gastric cancer." (PMID 41516419, 2026). "Currently, no systematic studies have examined the combination of RNF180 and SFRP2 for gastric cancer diagnosis, nor has the effect of different models on sensitivity been investigated." (PMID 39541711, 2024). "However, the role Wnt-antagonist genes including SFRP1, SFRP2, SFRP4, and SFRP5 in gastric cancer remains poorly defined." (PMID 17848950, 2007). "The frequent silencing of SFRP2 by methylation in gastric cancer but not in adjacent gastric mucosa suggests a potential tumour suppressor role of this gene." (PMID 17848950, 2007). "H. pylori infection was detected in 59% of gastric cancer tissues with methylation in SFRP2 gene and 43% of gastric cancer tissues without SFRP2 methylation (P=0.69)." (PMID 17848950, 2007).
gastric cancer (continued). "Among the four SFRPs, only SFRP2 was significantly downregulated in gastric cancer as compared to adjacent non-cancer samples (P<0.01)." (PMID 17848950, 2007). "Although widely expressed in non-cancer samples, SFRP2 is silenced by methylation in gastric cancer samples." (PMID 17848950, 2007). "The results showed that the methylation of SDC2, SFRP2, TERT, and RASSF2 has a certain sensitivity and high specificity in GC screening, which is a potential fecal biomarker of gastric cancer." (PMID 35309131, 2022). "It thus appears that epigenetic alteration of SFRP2 is present in the pre-neoplastic stage even in patients without gastric cancer, which may be an important mechanism leading to malignant transformation." (PMID 17848950, 2007). "To verify the MSP findings and to study the extent of promoter methylation of SFRP2, we performed high-resolution bisulphite genomic sequencing in the seven cell lines, four gastric cancers with low or silenced SFRP2 expression, and in their adjacent non-cancer tissues." (PMID 17848950, 2007). "To determine the onset time of SFRP2 methylation in the gastric carcinogenesis process, we examined endoscopic gastric specimens containing foci of intestinal metaplasia, a pre-neoplastic lesion, from patients without gastric cancer." (PMID 17848950, 2007). "However, the roles of SFRP2+ fibroblasts, MYH11+ fibroblasts, CD234+ endothelial cells and CD69+ fibroblasts are not clear in gastric cancer." (PMID 37649598, 2023). "Fourth, and most importantly, only SFRP2, but not SFRP1 silencing by promoter methylation was observed in oral SSC and gastric cancer, and promoter methylation is significantly higher in SFRP2 than SFRP1 in cervical cancer, as well as in cervical adenocarcinoma." (PMID 22384081, 2012).
melanoma (28 papers, 2016 to 2025). A malignant, usually aggressive tumor composed of atypical, neoplastic melanocytes. "However, a growing number of studies have shown that SFRP2 is associated with metastasis, poor prognosis and treatment resistance in a variety of malignant diseases, including melanoma, prostate cancer and glioma." (PMID 38116696, 2023). "sFRP2 also triggers a multi‐step signaling cascade in melanoma cells, leading to a reduction in β‐catenin and MITF, and consequently, the loss of a key redox effector, apurinic/apyrimidinic endonuclease 1 (APE1)." (PMID 41085102, 2025). "Another study suggested that recombinant SFRP2 treatment enhances angiogenesis in melanoma tumors, an effect that can be reversed by adding anti-SFRP2 antibodies." (PMID 39850884, 2024). "Within an aging microenvironment, sFRP2 has been identified as a driver of melanoma metastasis and resistance to therapies." (PMID 39494300, 2024). "H19 plays a critical role in regulating tumor plasticity in neuroendocrine prostate cancer, while SFRP2 in the aged microenvironment drives melanoma metastasis and therapy resistance." (PMID 37795080, 2023). "In studies on melanoma and chronic myocardial ischemia, elevated SFRP2 was found to be a crucial component of pathological vascular proliferation; VEGF antagonism by advanced pathological vascular proliferation did not limit angiogenesis." (PMID 37517049, 2023). "Secreted frizzled-related protein 2 (sFRP2) is a Wnt-antagonist highly secreted by aged fibroblasts and involved in the development of BRAFi resistance in melanoma cells." (PMID 34067929, 2021). "Using a different approach, the treatment of melanoma cells with recombinant SFRP2 also inhibited the expression of β-catenin." (PMID 33140138, 2021). "sFRP2 promotes the loss of APE1, a key redox effector, in melanoma cells by decreasing the levels of β-catenin and microphthalmia-associated transcription factor (MITF)." (PMID 32411704, 2020). "Aged dermal fibroblasts secrete more of the Wnt antagonist SFRP2 to suppress β-catenin in melanoma cells and drive melanoma metastasis." (PMID 33373316, 2020). "Moreover, the age-related rise in sFRP2 also bolsters angiogenesis and metastasis in melanoma cells." (PMID 40331942, 2025). "Animal experiments have shown that the melanoma cell line Yumm1.7 derived from a BrafV600E/Cdkn2a−/−/Pten−/− mouse model of melanoma grows slowly but aggressively in aged mice with increased angiogenesis and metastases due to the age-related increase in the Wnt antagonist sFRP2." (PMID 36135194, 2022). "Pro-angiogenic data were also be obtained from in vivo mouse models, in which melanoma tumors treated with recombinant SFRP2 showed enhanced angiogenesis, which could be reversed by the addition of an anti-SFRP2 antibody." (PMID 33140138, 2021). "It has been proposed that elevated level of sFRP2, a Wnt antagonist, secreted by aged fibroblasts could facilitate the acquisition of a metastatic, therapy-resistant state of melanoma." (PMID 33212834, 2020). "Furthermore, the increase in sFRP2 endows melanoma cells with the capacity to resist targeted therapy and metastasis." (PMID 32411704, 2020). "Moreover, sFRP2-mediated inhibition of β-catenin leads to reduced melanoma response to vemurafenib." (PMID 33036192, 2020). "In melanoma, epigenetic regulation of Wnt antagonists such as Dickkopf proteins (DKKs), Wnt inhibitor factor-1 (WIF1) and soluble frizzled-related protein-2 sFRP2 contributes substantially to cell-autonomous activation of Wnt/β-catenin signaling." (PMID 33212834, 2020). "Reduction of sFRP2 enhances the canonical WNT-signaling, whereas demethylation of its promoter inhibits the nuclear retention of β-catenin in melanoma cells and suppresses invasion." (PMID 32659938, 2020). "Studies have suggested that sFRP2 acts as a critical factor driving pathological angiogenesis in melanoma independent of VEGF43–45." (PMID 41258071, 2025).
colon cancer (19 papers, 2008 to 2025). "First, our result showed that patients with SFRP2 hypermethylation or co-hypermethylation of SFRP1 and SFRP2 had a lower risk of death in groups of ≥45 years old, male, colon cancer and TNM staging III-IV in traditional univariate and multivariate Cox." (PMID 31830937, 2019). "Additionally, SFRP2 was implicated, and recent immunohistochemistry work has linked this gene as a possible early biomarker of pancreatic and colon cancer." (PMID 37895248, 2023). "Except for the negative correlation between the relative methylation level of SFRP2‐1 and colon cancer, the relative methylation levels of the other 8 CpG sites were positively correlated with colon cancer." (PMID 38868913, 2024). "BGN, COL1A1, and SFRP2 were upregulated DEGs at 1-cm tissue in our study and these three DEGs were present in the stromal gene group of Connell model related to colon cancer recurrence." (PMID 38062443, 2023). "Another study reported that genistein down-regulates an onco-miRNA-miR-1260b which targets sFRP2 in colon cancer cells." (PMID 34289845, 2021). "Results from our study show a potential value of SFRP2 and COL1A1 to identify patients at high risk of colon cancer recurrence and metastatic disease." (PMID 33670920, 2021). "BRB anthocyanins decreased the expression of DNA methyltransferase and demethylated the hypermethylated promoters of the secreted frizzled-related protein 2 (SFRP2) gene to induce colon cancer carcinogenesis in the AOM-DSS mouse model." (PMID 34679735, 2021). "For colon cancer patients, SFRP2 hypermethylation patients and co-hypermethylation of SFRP1 and SFRP2 patients had a significantly favorable outcome through multivariate Cox regression, PS-1 and PS-2 analysis." (PMID 31830937, 2019). "Some of these inhibitors are Wnt target genes, for example, DKK4, an inhibitor that is expressed in human colon cancer, and SFRP2, a secreted Wnt inhibitor induced by Wnt4 in the developing kidney." (PMID 28183841, 2017). "Certainly, the role of SFRP2 in the context of colon cancer requires investigation and may represent a therapeutic target." (PMID 33670920, 2021). "This study reports that CAFs isolated from colon cancer tissue, TGF-β1-induced CAFs, or HCT116 co-cultured CAFs secrete more cytokines and growth factors represented by IGF1, ELN, and SFRP2." (PMID 40659611, 2025). "- Overexpression of miR-766 contribute to inhibition of colon cancer development by decreasing methylation of tumor suppressor genes including DKK2, WIF1, SFRP1, and SFRP2." (PMID 37205191, 2023). "For colon cancer, patients with promoter hypermethylation of SFRP1 or co-hypermethylation of SFRP1 and SFRP2 had higher overall survival." (PMID 31830937, 2019). "Moreover, the extracellular Wnt antagonists Sfrp1 and Sfrp2 are upregulated by Shh-Gli signalling in different experimental systems and nuclear accumulation of the Wnt transducer β-catenin and the Shh transducer Gli1 are inversely correlated in a human colon cancer cell line." (PMID 19732418, 2009). "In colon cancer cell lines, anthocyanin extract from BRB suppressed the activity and protein expression of DNA methyltransferase enzymes, DNMT1 and DNMT3B, and demethylated WNT upstream regulators, CDKN2A, SFRP2, SFRP5, and WIF1." (PMID 34679735, 2021). "In the AOM/DSS colon cancer mouse model, the BRB anthocyanin extraction in the diet decreased tumor multiplicity, modulated the composition of gut commensal microbiota, and changed the inflammation index and the methylation status of the SFRP2 gene." (PMID 34679735, 2021). "Finally, down-regulation of SIRT1 in breast and colon cancer cell lines leads to re-expression of the Wnt pathway inhibitors, SFRP1 and SFRP2 (Secreted Frizzled-like Proteins 1 and 2), which are frequently inactivated in human cancers through epigenetic means, as discussed in greater detail below." (PMID 23799088, 2013).
adenoma (18 papers, 2008 to 2023). A neoplasm arising from the epithelium. "Here, we report significantly increased hypermethylation frequencies for two secreted frizzled-related proteins, SFRP1 and SFRP2, in LS-associated adenomas and carcinomas when compared to normal colon." (PMID 26203307, 2015). "In addition, we found variants in genes implicated in Wnt signalling, such as LRP5, WNT3A, and SFRP2, which shows a significantly increased level of methylation in adenomas." (PMID 34843512, 2021). "In the current study, we observed increased methylation of APC2 and decreased methylation of SFRP2 in adenomas in Apcmin/+ mice." (PMID 26101583, 2015). "Individually, ITGA4, SFRP2, and p16 were detected in 36.7%, 60.0%, and 40.0% of CRCs and 16.0%, 44.0%, and 24.0% of adenomas, respectively." (PMID 22969796, 2012). "SFRP2 hypermethylation was subsequently confirmed by other studies in stool samples from patients with CRC, adenomas, and advanced precancerous stages." (PMID 38248446, 2023). "Another DNA methylation study specifically evaluated methylation in four genes (SFRP1, SFRP2, SDC2 and PRIMA1), with an AUC of 0.93 for the multi-marker panel for detecting adenoma." (PMID 34503217, 2021). "DNA was available for eight such adenomas, and 3/8, 4/8, 6/8, and 2/8 revealed hypermethylation of IGF2, NEUROG1, SFRP1, and SFRP2, respectively." (PMID 26203307, 2015). "To investigate the relation between methylation of SFRP2, WIF-1, DKK3 and SOX17 and the anatomical location of the adenoma, we divided all the adenomas into left- and right-sided adenomas." (PMID 24350795, 2013). "Methylation of SFRP2, WIF-1, DKK3 and SOX17 was significantly higher in carcinomas as well as both types of adenomas compared to normal colorectal mucosa." (PMID 24350795, 2013). "Extensive methylation of SFRP2 and RASSF2 was more common in colorectal tumours, with a sensitivity of 75% among CRC patients and 44% with advanced adenomas." (PMID 22969796, 2012). "We discovered widespread hypermethylation of the Wnt antagonists SFRP1, SFRP2, SFRP5, DKK2, WIF1 and SOX17 in the transition from normal to adenoma with only the Wnt antagonists SFRP1, SFRP2, DKK2 and WIF1 showing further significant increase in methylation from adenoma to carcinoma." (PMID 25432628, 2014). "The present study focussed on promoter methylation of four known Wnt-pathway antagonists (SFRP2, WIF-1, DKK3 and SOX17), in polypoid and nonpolypoid adenomas, and its possible association with other molecular events that can play a role in Wnt-pathway activation." (PMID 24350795, 2013). "For APC methylation as well as for chromosome 5q loss, no relation was found with the promoter methylation results for SFRP2, WIF-1, DKK3 and SOX17 when combining both adenomas types or in nonpolypoid adenomas or polypoid adenomas, separately." (PMID 24350795, 2013). "In addition, ALDH1A3, COL1A2, FADS1, SFRP2, SULF1, and THBS2 were found to be significantly (p < 0.01) differentially expressed in tumour samples but not in adenomas compared to healthy samples." (PMID 26482433, 2015).
myocardial infarction (16 papers, 2012 to 2024). Gross necrosis of the myocardium, as a result of interruption of the blood supply to the area, as in coronary thrombosis. "Fourth, in rodents, Sfrp2 is involved in fibrosis associated with myocardial infarction." (PMID 22859963, 2012). "SFRP2 was found to induce endothelial tube formation, reduce myocardial infarction area and improve cardiac dysfunction." (PMID 38188253, 2023). "In myocardial infarct-related studies, inhibition of the Wnt pathway using sFRP1, sFRP2, or sFRP4 was shown to reduce fibrosis and improve cardiac function." (PMID 37609444, 2023). "For example, in animal models of myocardial infarction, SFRP2 gene deletion attenuated fibrosis and improved cardiac function, while treatment with SFRP2 antibody reduced apoptosis and fibrosis." (PMID 33015048, 2020). "Their study found that the degree of myocardial fibrosis after myocardial infarction was reduced in sFRP2 knockout mice compared with normal mice." (PMID 32071544, 2020). "Transplantation of BMSCs-IGF-1 into myocardial infarction rats greatly reduced infarct volume than BMSCs-NC, with significantly greater expression of SFRP2 and β-catenin." (PMID 31918758, 2020). "The Sfrp2 overexpression obviously disturbed the regulatory effects of Safe shRNAs in both the in vitro cultured cardiac fibroblasts and myocardial infarction-induced fibrosis." (PMID 31695768, 2019). "sFRP2 is a part of the sFRP family and has been previously shown to reduce fibrosis and improve the left ventricular functionality of the heart in the rat myocardial infarction model." (PMID 30151071, 2018). "Intramyocardial injection of MSCs that overexpress sFRP2 leads to strengthened engraftment and vascular density, decreased infarct size, and enhanced cardiac function after myocardial infarction in mice." (PMID 25101130, 2014). "One study reported that blocking SFRP2 markedly reduces the extent and severity of fibrosis in mice with experimentally-induced myocardial infarction." (PMID 24386373, 2013). "Secreted frizzled-related protein 2 (Sfrp2) was recently reported to play a critical role on cardiac fibrosis after myocardial infarction (MI), partially through activating bone morphogenic protein 1 (BMP1) to initiate a feed-forward loop between TGF-β and BMP1 7-9." (PMID 31695768, 2019). "Additionally, wnt3a has been published in previous studies of myocardial infarction-induced apoptosis, where increased levels of wnt3a were observed after the infarct was generated, whereas sFRP2 administration attenuated this wnt3a activity." (PMID 30151071, 2018). "sFRP-2 has also been shown to play a role in myocardial infarct healing." (PMID 22967504, 2012). "Another study in mice demonstrated that gene expression of fibroblasts was skewed toward Ki-67, COL1A2, collagen type III alpha 1 chain (COL3A1), collagen type V alpha 1 chain (COL5A1), SPARC, secreted frizzled related protein 2 (SFRP2), and DKK3 following myocardial infarction." (PMID 35548426, 2022).